MMP8 (matrix metallopeptidase 8)
Diseases named in the same sentence as MMP8 in open-access papers (continued):
Sharing a sentence is not in itself a finding about the gene and the disease.
periodontitis (continued). "In saliva, combinations of IL-1β, IL-6, and MMP-8 have superior properties for the detection of periodontitis." (PMID 39684335, 2024). "According to these studies, MMP-8 has great potential in detecting periodontitis compared to traditional methods, but it must be assayed with oral rinse fluid in its active form." (PMID 38473967, 2024). "Peri-implantitis had a 97% higher concentration of matrix metalloproteinases (MMP), such as MMP-8, but chronic periodontitis had just a 78% increase compared to healthy gingiva." (PMID 39605747, 2024). "Comparison of salivary matrix metalloproteinase‐8 (MMP‐8) levels before and after periodontitis treatment in patients." (PMID 38433295, 2024). "By means of the analysis of 10 researches, including 485 periodontitis patients and 379 healthy controls, Lin Zhang find that the salivary MMP-8 levels were significantly higher in periodontitis patients compared with healthy controls." (PMID 38684998, 2024). "MMP-8 concentrations in the saliva of patients with periodontitis were four times higher than in healthy individuals." (PMID 38473967, 2024). "The aMMP-8 biomarker was therefore deemed as being more precise and effective than the conventional BOP and total MMP-8 analysis, especially in its ability to identify subclinical periodontitis/pre-periodontitis." (PMID 39273368, 2024). "An emerging focus is now on use of active MMP-8 as a biomarker for diagnosing, grading, screening, and evaluating treatment responses in periodontitis." (PMID 39273368, 2024). "This was the first study to systematically investigate periodontitis and gingivitis patients' MMP-8 results, with regard to predicting and assessing future periodontal disease severity and providing a basis for measuring oral health." (PMID 39641024, 2024). "MMP-8 concentrations were observed in subjects with more severe forms of periodontitis compared to those with moderate and mild forms of the disease." (PMID 38473967, 2024). "As the presence of MMP-8 in oral fluid and serum was detected in patients with periodontitis, MMP-8 has been proposed as a sensitive biomarker, health indicator, and biomarker for response to drug treatment, such as doxycycline as an MMP inhibitor." (PMID 38254696, 2024). "This systematic review and meta-analysis aims to evaluate the salivary MMP-8 level of periodontitis and gingivitis cases compared to healthy controls." (PMID 39641024, 2024). "According to this study, salivary IL-1β and MMP-8 are potential biomarkers to identify periodontitis and gingivitis." (PMID 38086426, 2024). "The present systematic review and meta-analysis aimed to determine if MMP-8 can distinguish between periodontal health and gingivitis, between periodontal health and periodontitis, and between periodontitis and gingivitis." (PMID 39641024, 2024). "Matrix metalloproteinase (MMP)-8, also known as neutrophil collagenase or collagenase-2, is among the key proteolytic enzymes involved in the destruction of tooth-supporting periodontitis-affected soft and hard tissues." (PMID 39273368, 2024). "Saliva biomarkers can be used to diagnose periodontitis, assess disease severity, and monitor the response to treatment, and the most promising biomarker appears to be MMP-8." (PMID 39641024, 2024). "Nonetheless, previous in vivo studies have also revealed rather low or barely detectable de novo transcriptional expression of MMP-8 RNA in the diseased periodontitis-affected gingiva and peri-apical periodontitis-affected lesions." (PMID 38786309, 2024). "During gingivitis, there can be a slightly elevated MMP-8 level in gingival crevicular fluid, but in the latent form, during active phases of periodontitis, it is further elevated and mostly converted into the active form." (PMID 38474009, 2024).
periodontitis (continued). "MMP-8 showed the highest significant difference from the investigated biomarkers between periodontitis and healthy controls (ratio: 9.69, p < 0.001) and showed the second highest difference between gingivitis and healthy controls (ratio: 3.56, p = 0.001)." (PMID 39641024, 2024). "MMP-8 assays are performed in gingival fluid or saliva, and MMP-8 levels have been shown to be higher in patients with periodontitis compared to healthy subjects and correlated with some clinical parameters of the condition and the severity of the disease." (PMID 38473967, 2024). "According to most studies, patients with periodontitis have higher concentrations and an elevated enzymatic activity of MMP-8 in the gingival fluid compared to healthy individuals." (PMID 38473967, 2024). "Among all MMPs, MMP‐8 is known as a significant marker in chronic periodontitis, and it is possible to detect it in saliva and gingival crevicular fluid." (PMID 38433295, 2024). "Several studies have shown that MMP-8 and IL-1β are the most reliable markers of persistent periodontitis, and the Helsinki group has developed point-of-care tests (PerioSafe®, ImplantSafe®) to assess salivary MMP-8 levels." (PMID 39275315, 2024). "Based on our results, salivary MMP-8 level is significantly different in patients with periodontitis, gingivitis and healthy periodontium, with periodontitis cases having the highest and healthy controls having the lowest values." (PMID 39641024, 2024). "In this study, we investigated the level of MMP‐8 in the saliva of people with periodontitis and diabetes in a population with different heredity, geographical factors, race, and so on." (PMID 38433295, 2024). "Based on 20 eligible studies (n = 1725), patients with periodontitis presented significantly higher MMP-8 levels (MD = 273.26 ng/ml, CI: 194.42; 352.10)." (PMID 39641024, 2024). "The levels of MMP-8 can also be affected by medications, such as the low doses of drugs that take part in the conventional treatment of both peri-implantitis and periodontitis." (PMID 37371608, 2023). "In particular, MMP8 has a protective role during the inflammatory response to various agents, despite the abnormal levels of this gene indicating chronic periodontitis." (PMID 36835067, 2023). "In vivo studies of F1 in the experimentally induced periodontitis in rats demonstrated its effectiveness in improving the clinical parameters and reducing the salivary MMP-8 levels." (PMID 36839899, 2023). "Some studies assessed the influence of SRP on clinical parameters and IL1β, IL8, and MMP-8 levels in GCF in patients with chronic periodontitis." (PMID 38249256, 2023). "DS periodontitis patients showed a positive correlation with highly statistically significant values (p< .000) and increased MMP8 and MMP9." (PMID 37448427, 2023). "The same was observed in the concentrations of MMP-8, a collagen matrix degradation enzyme present in the early stages of periodontitis, originating from polymorphonuclear leukocytes." (PMID 37026605, 2023). "Recently, MMP-8 has been considered to be one of the most promising biomarkers for early detection of periodontitis and for its progression and prognosis of treatment." (PMID 37371608, 2023). "More notably, in oral fluids MMP-8 can also serve as a predictive and preventive adjunctive biotechnological tool, avoiding or reducing the evolution of gingivitis or mucositis to periodontitis or peri-implantitis, respectively." (PMID 36997949, 2023). "MMP-8 is the most prevalent collagenolytic protease in the diseased periodontium and aMMP-8 the major mediator of periodontitis." (PMID 38275388, 2023). "In this way, MMP-8 and MMP-9 are extremely valuable diagnostic tools in treating periodontitis, while MMP-13 affects the activity of osteoclasts and bone resorption, contributing to the destruction of the periodontal tissue." (PMID 37047877, 2023).
periodontitis (continued). "MMP-8 has been proposed and validated as a biomarker for the early diagnosis of periodontitis, with chairside equipment developed for regular clinical usage." (PMID 36839899, 2023). "The statistical decrease in aMMP-8 levels post-periodontal treatment suggests that active tissue destruction, along with clinical disease activity, is reduced, confirming the role of MMP-8 in periodontitis pathogenesis." (PMID 36900047, 2023). "Lower levels of MMP-8 were detected during the examination carried out after the periodontitis treatment (1912.19 pg/mL) compared with the examination previous to the periodontitis treatment (2272.08 pg/mL, p = 0.001)." (PMID 36902236, 2023). "In general terms, the average levels of MMP-8 gradually decreased during the 2 years of orthodontic treatment, at all the analyzed times being lower than those detected during periodontitis." (PMID 36902236, 2023). "Moreover, at all the analyzed time-points of the orthodontic treatment, the RANKL/OPG ratio and MMP-8 levels, which are directly associated with alveolar bone resorption and soft tissue degradation, respectively, were maintained below those detected during previous periodontitis." (PMID 36902236, 2023). "In this line, the levels of MMP-8 at the periodontitis examination were higher in the vestibular periodontal site in comparison to the other sites, which is consistent with the protruded pathological position of the affected teeth." (PMID 36902236, 2023). "It is considered in the literature that MMP-8 is a biomarker of significance in the new classifications of periodontitis and peri-implantitis." (PMID 36997949, 2023). "Among the 23 types of MMPs already identified, the upregulation of MMP-8 and -9 has been related to periodontitis and peri-implantitis and it is associated with disease progression and bone loss." (PMID 37545886, 2023). "The immunohistochemically labeled cells for MMP-13 and for MMP-8 were higher in density in periodontitis gingiva when compared with healthy control tissue (p < 0.01)." (PMID 37371608, 2023). "MMP-8 is notably indicative of periodontal inflammation, and it is crucially involved in the progression of periodontitis and promotes the development of periodontal diseases at the active site of periodontal inflammation." (PMID 37794378, 2023). "Our findings revealed elevated MMP8 and MMP9 in DS patients with periodontitis, indicating an increased risk for early development of destructive forms of periodontal disease in this population." (PMID 37448427, 2023). "A review of 61 articles regarding potential use of MMP-8 as a biomarker of periodontitis shows this enzyme as a strong candidate for an indicator of periodontal inflammation." (PMID 36245042, 2022). "Elevated levels of MMP‐8 are found in the saliva and gingival crevicular fluid as well as in the circulation of periodontitis patients." (PMID 35315933, 2022). "MMP-8 and CTX-I are vital bone-loss biomarkers, indicating soluble UA is a risk factor for periodontitis." (PMID 36466813, 2022). "Enhanced expression and activation of matrix metalloproteinase 8 (MMP‐8) is one of the key factors responsible for tissue degradation during periodontitis." (PMID 35315933, 2022). "The study findings revealed that participants with severe periodontitis had increased concentrations of IL-1β and MMP-8, while smokers also had slightly reduced concentrations of IL–8 and MMP-8." (PMID 35626325, 2022). "Active MMP-8 (aMMP-8) is the major mediator of periodontitis and peri-implantitis tissue destruction." (PMID 35757444, 2022). "The significantly higher salivary MMP‐8 levels detected in gingivitis and periodontitis participants compared with healthy participants by all the three assays, aligns with previous studies that have utilized IFMA, ELISA and quite recently the biosensor." (PMID 35304757, 2022).
periodontitis (continued). "Matrix metalloproteinase-8 (MMP8) and interleukin (IL)-1beta, the most studied biomarkers in the periodontitis field, demonstrate convincing clinical diagnostic validity." (PMID 36457739, 2022). "The fact that in the post hoc analyses, the assays clearly demarcated MMP‐8 levels between health and gingivitis, health and periodontitis, and gingivitis and periodontitis is relevant." (PMID 35304757, 2022). "Salivary biomarkers (MMP-8, MMP-9, and TIMP-1) exhibited a high diagnostic accuracy in discriminating between periodontal health from periodontitis in general and S1 periodontitis." (PMID 36292174, 2022). "This showed that a salivary MMP‐8 level at 214.40 ng/ml or above is an approximate cut‐off value, which indicates periodontitis." (PMID 35769040, 2022). "In fact, MMP-8 (or collagenase 2) has been referred to as one of the most promising biomarkers for periodontitis in oral fluids." (PMID 35163727, 2022). "All the assays demonstrated significantly higher salivary MMP‐8 concentrations in participants with periodontitis versus gingivitis, periodontitis versus health, and gingivitis versus health (all p < .05)." (PMID 35304757, 2022). "Increased levels of IL-6 and MMP-8 have been observed in the saliva of patients with chronic periodontitis." (PMID 36275775, 2022). "Meanwhile, the AUCs between periodontal health and periodontitis S1 for MMP-8, MMP-9, and TIMP-1 were 0.964 (p value = 0.0001), 0.938 (p value = 0.001), and 0.902 (p value = 0.002), respectively." (PMID 36292174, 2022). "All tested biomarkers (MMP-8, MMP-9, and TIMP-1) and ratios of MMP-8/TIMP-1 and MMP-9/TIMP-1 showed statistically significant diagnostic accuracy in differentiating between periodontal health and periodontitis." (PMID 36292174, 2022). "Regarding individual biomarkers, IL-1β, IL-6, and MMP-8 levels were significantly higher in periodontitis patients (p ≤ 0.001, p < 0.05, respectively)." (PMID 35368315, 2022). "Salivary MMP‐8 can distinguish between periodontitis and healthy individuals with an accuracy of about 80%." (PMID 35769040, 2022). "The ability of the assays to detect changes in salivary MMP‐8 levels before and 6 months after non‐surgical periodontal treatment was also evaluated in a sub‐set of twenty periodontitis patients." (PMID 35304757, 2022). "MMP-8 has been reported as a collagenase that can destroy the extracellular matrix in the soft tissue around teeth, which results in periodontitis." (PMID 35955695, 2022). "S-nitrosoglutathione, a nitric oxide donor, reduced the MMP-1 and MMP-8 in the periodontium of Wistar rats in a ligature-induced periodontitis model." (PMID 36012195, 2022). "Both the biosensor and the IFMA (aMMP‐8) detected a periodontal treatment effect among the periodontitis participant, as indicated by the reduced salivary MMP‐8 levels after 6 months." (PMID 35304757, 2022). "MMP-8 (collagenase-2) is the major tissue-destructive MMP in the periodontitis-affected gingiva, and the elevated MMP-8 levels have also been demonstrated in the peri-implantitis sites." (PMID 35055373, 2022). "A recent meta-analysis reported significantly higher levels of salivary MMP-8 in periodontitis patients compared to healthy participants." (PMID 35268009, 2022). "According to the current literature, immunofluorometric assay (IFMA) was utilized to assess active MMP‐8 and can be employed as a staging and grading biomarker in the new classification system of periodontitis." (PMID 35769040, 2022). "The comparative performance of the biosensor and the other assay methods for salivary MMP‐8 in terms of distinguishing periodontal health, gingivitis, and periodontitis was assessed." (PMID 35304757, 2022). "Nevertheless, MMP-8 analyses should be used with caution, as some studies show higher MMP-8 levels in healthy individuals, while others show the same results in patients with periodontitis." (PMID 35877858, 2022).
periodontitis (continued). "The aim of our study was to evaluate the presence of S100A8/A9/A12, MMP8, and CFH polymorphisms in periodontitis and to find out if polymorphisms of these genes affect the concentrations of corresponding proteins or marker of complement activation in saliva." (PMID 35315933, 2022). "In fact, MMP-8 (or collagenase 2) is currently one of the most promising biomarkers for periodontitis in oral fluids." (PMID 35163727, 2022). "In summary, this study has reaffirmed the ability of the SAW biosensor, IFMA, and ELISA assays to detect MMP‐8 levels in saliva to distinguish participants with periodontal health, gingivitis, and periodontitis." (PMID 35304757, 2022). "Saliva is an easy and non-invasive diagnostic fluid that is useful for the diagnosis of early periodontitis, and the possibility of early diagnosis of periodontitis in adolescents, especially boys, based on elevated salivary MMP-8 levels has been reported." (PMID 36361498, 2022). "Overall salivary MMP-8 levels were significantly higher in periodontitis patients compared with healthy controls." (PMID 36361498, 2022). "The biosensor, IFMA, and ELISA assays differentiated between periodontal health, gingivitis, and periodontitis based on salivary MMP‐8 levels." (PMID 35304757, 2022). "MMP‐8 (collagenase 2), a collagenolytic enzyme plays a significant role in tissue destruction in periodontitis as it instigates the digestion of type I collagen, which is the most dominant interstitial type in the periodontal tissues." (PMID 34800007, 2022). "One of the most studied biomarkers of periodontitis is matrix metalloproteinase (MMP)-8, a collagenase enzyme involved in the destruction of periodontal tissues and progression of periodontitis." (PMID 35270821, 2022). "Regarding MMP-8, despite being higher in concentration in periodontitis subjects compared to the healthy subjects, the difference between the groups was not statistically significant (p=0.059)." (PMID 35368315, 2022). "Another review, performed by Brazilian researchers, also confirmed the potential of MMP-8 as a prognostic marker for development of periodontitis." (PMID 36245042, 2022). "In periodontitis and peri-implantitis, MMP-8 is regulated as inductive neutrophil degranulating stimuli and zymogen activation and subsequently inhibited rather than translationally by the de-novo expression." (PMID 35757444, 2022). "Another well-known biomarker of periodontitis is metalloproteinase-8 (MMP-8), a proteolytic enzyme that is involved in the degradation of periodontal connective tissue." (PMID 35893412, 2022). "A search for potential markers of periodontitis onset or progression resulted in many potential candidates for such agent—among others matrix metalloproteinase (MMP)-8, IL-1, IL-6, tumor necrosis factor (TNF)-α, PGE2." (PMID 36245042, 2022). "The significant reduction in aMMP‐8 post‐treatment detected by the IFMA further corroborates the key role of MMP‐8 in the pathogenesis of periodontitis." (PMID 35304757, 2022). "Recently, the potential utility of the active form of MMP‐8 (aMMP‐8), as a biomarker in the oral‐systemic link was highlighted, due to the contribution of periodontitis to the inflammatory burden in various systemic diseases and conditions." (PMID 35304757, 2022). "Recent systematic reviews focused on IL-1beta, IL-6 and MMP-8 as promising candidates for early diagnosis of periodontitis." (PMID 35327490, 2022). "Chlorhexidine chip intraoral application following scaling and root planning lowered MMP-8 levels in the gingival crevicular fluid of chronic periodontitis patients." (PMID 36012195, 2022). "The results from the current study were inconsistent with those of another study which recommended the use of MMP-8 in the staging and grading of periodontitis." (PMID 36292174, 2022).